ESR1 (estrogen receptor 1)
Diseases named in the same sentence as ESR1 in open-access papers (continued):
Sharing a sentence is not in itself a finding about the gene and the disease.
prostate carcinoma (continued). "It has been found previously that ESR2 is highly expressed in prostate cancer lines, while ESR1 is expressed in less extend." (PMID 30361641, 2018). "ESR1 KO/TRAMP mice were less likely to develop aggressive prostate cancer compared to WT/TRAMP mice (5% vs. 19% incidence rate)." (PMID 26971397, 2016). "Oestrogen plays a vital role in mammary gland development and is also involved in prostate cancer progression, exerting its biological actions through the oestrogen receptors ESR1 and ESR2 (refs 8, 9)." (PMID 26443449, 2015). "Currently, a wide range of genes have been identified have some risk associations with prostate cancer, such as AR, CYP17/19, NOS, PSA, ESR1/2, etc." (PMID 23805288, 2013). "Methylation of the oestrogen receptor alpha (ESR1) gene, whose downregulation has been suggested to play a role in cancer metastasis, has also been documented in prostate cancer." (PMID 19002169, 2009). "Furthermore, the overexpression of ESR1 has been connected to the development and advancement of several other cancer types, including gastric cancer, prostate cancer, colorectal cancer, and lung cancer." (PMID 40149497, 2025). "Polymorphisms in ESR1, such as PvuII (rs2234693 T > C), XbaI (rs9340799 A > G), and T594T (rs2228480 G > A), have been reported to be significantly associated with cancer development, particularly in HCC and prostate cancer, as confirmed by this study." (PMID 40864066, 2025). "The prevalence of ESR1 (which encodes ERα) and ESR2 (which encodes ERβ) mutations was 3% (5/150) in individuals with metastatic or advanced PCa, whereas it was 2% (11/492) in patients with early prostate cancer, according to a genomic dataset." (PMID 36979805, 2023). "Previous studies from our laboratory have already shown that, in androgen-independent prostate cancer cells PC-3 and DU-145, estrogen receptors (ER) ERα (ESR1) and ERβ (ESR2) are mostly located outside the nucleus of these cells, indicating the activation of rapid signaling pathways." (PMID 33503805, 2021). "Interestingly, miR-31-5p was the miRNA showing the most negative correlation with AR (Pearson score −0.43 and p-value = 0.0026) and concomitant positive correlation with ESR1 (Pearson score 0.49 and p-value = 0.0004) in our cohort of prostate cancer tissues." (PMID 32041153, 2020). "Moreover, there is evidence that ESR1 antagonists can repress prostate cancer tumorigenicity and that abiraterone can activate estrogen receptor." (PMID 32041153, 2020). "Hence, the results were in good agreement with it that ESR1 acted as a major driver of anti-carcinogenic efficiency in prostate cancer." (PMID 30918758, 2019). "What’s more, all naringenin-mediated proteins were subject to Kyoto Encyclopedia of Genes and Genomes (KEGG) enrichment analysis by the Database for Annotation, Visualization and Integrated Discovery, which resulted in three ESR1-related signaling pathways and prostate cancer pathway." (PMID 30918758, 2019). "A hypothesis currently being considered is that naringenin could regulate prostate cancer via ESR1 signaling axis." (PMID 30918758, 2019). "In certain genetic backgrounds, WT mice show a greater incidence of prostate cancer than ESR1 KO, which may be due to increased abundance of P. acnes." (PMID 26971397, 2016). "ESR1 XbaI (A>G) polymorphism was confirmed to be associated with increased risk of prostate cancer among American population under the allele model, but not among Japanese and Indian populations." (PMID 23805288, 2013). "Genes involved in the signal transduction above are all target genes of highly expressed miRNAs in prostate cancer samples; therefore, the expression of ESR1 and ESR2 will be down-regulated which is in accordance with the previous report by Gamba and his co-authors." (PMID 24555436, 2013). "In addition, ESR1 is an oncogene that promotes the proliferation and metastasis of prostate cancer, and its expression is related to the poor prognosis of patients with prostate cancer." (PMID 35686089, 2022).
prostate carcinoma (continued). "Interestingly, for all the three independent datasets analyzed, an enrichment of up- and down-regulated transcriptional targets for both AR and ESR1 emerged, suggesting a possible interplay between these two proteins in controlling the neuroendocrine transdifferentiation process of prostate cancer." (PMID 32041153, 2020). "This study highlights the potential of SSA as a therapeutic agent for prostate cancer by identifying its key molecular targets (BCL2, ESR1, HIF1A, and STAT3) and validating its anti-proliferative and pro-apoptotic effects in PC3 cells." (PMID 39995416, 2025). "YKL-39 has also been shown to be elevated in estrogen receptor 1 (ESR1) mutant metastatic breast cancer and has been shown to be regulated by the androgen receptor in prostate cancer." (PMID 33968034, 2021). "The top 30 protein targets with high frequency were CCND1, EGFR, ESR1, and MYC, which can be used as the potential targets of XHP in the treatment of prostate cancer." (PMID 35342388, 2021). "Most of the genetic alterations in ESR1, PIK3CA, AKT1, and MAPK1 were amplifications, suggesting an excess expression in prostate cancer." (PMID 30918758, 2019). "Another example would be estrogen receptors (ESR1 and ESR2), against which 5 drugs were developed to cure breast and prostate cancers." (PMID 31803618, 2019). "In order to show the effect of ESR1 and ESR2 promoter methylation and demethylation on gene expression, prostate cancer cell lines LNCaP, DU145 and PC3 were treated with 5-aza-2′-deoxycytidine (AZA)." (PMID 29731970, 2018). "Our findings indicate that Ang1–7 reduced the expression of ESR1 and increased that of ESR2 in prostate cancer cells." (PMID 30361641, 2018). "A 48-hour incubation with this heptapeptide resulted in significantly decreased expression of ESR1 and a noticeable increase in the mRNA level of ESR2 in prostate cancer cells." (PMID 30361641, 2018). "Propionibacterium acnes, causative agent of chronic prostatitis possibly culminating in prostate cancer, is reduced in SFM of ESR1 KO compared to WT mice (P ≤ 0.0007)." (PMID 26971397, 2016). "Among upregulated genes, the gene Greb1 (growth regulating estrogen receptor binding 1), which is regulated by Esr1 in TM4 cells and primary Sertoli cells and is involved in hormone-responsive breast and prostate cancers, was increased by 3.5-fold only by the APAP + GEN mixture." (PMID 37443838, 2023). "Furthermore, decreased expression of ESR1 and a noticeable increase in ESR2 mRNA was observed in all prostate cancer cells." (PMID 32872192, 2020). "Another miRNA, miR-520a binds to the 3' UTR of target genes including Microtubule Affinity Regulating Kinase 2 (MARK2), Estrogen Receptor 1 (ESR1) at early-stage cancer and Suppressor of Zeste 12 (SUZ12) during advance-stage and ESR1 during CRPC progression of prostate cancer." (PMID 31756185, 2019). "ESR1 was the main target of most FDA approved drugs (represented by yellow hexagon) in the network, providing a molecular basis for potential clinical applications of naringenin to treat prostate cancer targeting ESR1." (PMID 30918758, 2019). "Firstly, we examined the significance of three hormone receptors: AR, ESR1, ESR2 in the biology of prostate cancer regarding the effect of their expression on tumor recurrence according to patient’s age (four age groups: ≤50, 51–60, 61–70, 70> years old) through disease-free survival (DFS) analysis." (PMID 29206234, 2017). "Since they are co-interacting with PARM1 and MYEF2, ESR1 and NR3C2 may also participate in prostate cancer along with the existent/potential targets." (PMID 25151146, 2014). "On the other hand thus far, no inherited variations in AR, estrogen receptor-1 (ESR1), or estrogen receptor-2 (ESR2) genes have been found associated with prostate cancer aggressiveness or with the efficacy of androgen deprivation in Caucasian populations." (PMID 22956944, 2012).
prostate carcinoma (continued). "The role of MARK2 with respect to prostate cancer was not yet been studied, while previous reports showed that ESR1 play protective roles in prostate cancer development, though still unknown." (PMID 31756185, 2019). "Therefore, a hypothesis is currently proposed that naringenin acts through a series of genes (ESR1, PIK3CA, AKT1, MAPK1, and AR) to control prostate cancer cell proliferation." (PMID 30918758, 2019). "WT and ESR1 KO mice typically do not develop prostate cancer." (PMID 26971397, 2016).
ovarian carcinoma (308 papers, 2007 to 2026). A malignant neoplasm originating from the surface ovarian epithelium. "Among Clone A-specific gains is an amplification of 6q25.1, containing ESR1 – an uncommon event in ovarian cancer that is associated with strong protein positivity and potential response to anti-hormone therapy." (PMID 41279090, 2025). "For ovarian cancer, ESR1 expression has been found to be associated with the loss of chromosome 1p and 16q." (PMID 38582811, 2024). "The hypermethylation of the ESR1 promoter is a hallmark of reduced ERα expression in ovarian cancer." (PMID 39796024, 2024). "ESR1 expressions are commonly downregulated in cell line cultures due to mechanisms such as epigenetic changes and mutations, especially in ovarian cancer cell lines." (PMID 38582811, 2024). "ESR1 expression has been associated with improved ovarian cancer survival and lower risk of macroscopic residual disease in endometrioid tumors." (PMID 36761962, 2023). "More specifically, eight plasma-cfDNA samples from patients with metastatic cancer and three plasma-cfDNA samples from patients with advanced ovarian cancer were found to be positive for ESR1 mutations." (PMID 35954453, 2022). "As for ovarian cancer, the cBioPortal cancer genomics database includes one ovarian serous cystadenocarcinoma study in which ESR1 mutations were detected in 0.8% of samples." (PMID 35954453, 2022). "Other notable findings include that ESR1 mutations in cluster 1357.1 are associated with high ESR1 in ovarian cancer, whereas AKT1 mutations in cluster 756.0 are associated with high AKT1 proteins." (PMID 33875650, 2021). "High expression of ESR1 has been associated with outcome for ovarian cancer after platinum-based therapy and also decreased on carboplatin treatment." (PMID 26964739, 2016). "Differential ESR1 binding is associated with outcome following breast cancer and altered ESR1 expression in ovarian cancer is associated with prognosis." (PMID 24171864, 2013). "The aim of this study was to demonstrate whether polymorphisms of the ESR1 gene rs2234693 and rs9340799 may be involved in the development of ovarian cancer." (PMID 41977420, 2026). "Polymorphisms rs2234693 and rs9340799 of the ESR1 gene may be associated with the occurrence of ovarian cancer." (PMID 41977420, 2026). "In ovarian cancer there have been just a few reports on the presence of ESR1 mutations." (PMID 35954453, 2022). "According to the comparative docking results, CASP3 and ESR1 were identified as the most potential molecular targets for mediating medicarpin’s anticancer activity in ovarian cancer, hence justifying their prioritization in further research." (PMID 41516052, 2025). "Both PAPSS1 and ESR1 gene expression are relatively sensitive markers for predicting the effect of platinum treatment on patients with ovarian cancer." (PMID 37684671, 2023). "ESR1 expression in ovarian cancer and epithelial normal ovary tissues is presented as a boxplot graph identified based on open-source TCGA and GTEx mRNA data using the GEPIA online tool." (PMID 37684671, 2023). "Among the PPI networks of SYNE1, CDK12, and PGS1, the ovarian and other cancer-related gene SYNE1 is located 19 kb downstream of ESR1, and it partially contributes to ovarian cancer." (PMID 34763659, 2021). "ESR1, reported in many solid malignancies, is frequently methylated in ovarian cancer cell lines, its methylation was also detected in cfDNA of high-grade serous ovarian cancer patients." (PMID 32192517, 2020). "Both primary tumors and paired ctDNA detected methylated ESR1 and the presence of ESR1 methylation correlated with better clinical outcome in ovarian cancer." (PMID 32536040, 2020). "Expression of ESR-2 in the chicken ovaries is very low and ovarian cancer has been reported to have a higher ESR1/ESR2 ratio in both chicken and women." (PMID 31128594, 2019).
ovarian carcinoma (continued). "Among all the patients with ovarian carcinomas harboring a methylation of OSMR or ESR1, β-value > 0.3 and M-value > −1.222, we found more patients dead of the disease than in the cases with a hypomethylation of these genes (p < 0.05)." (PMID 29882921, 2018). "NRF2 and ERα protein expression in ovarian cancer tissue was analyzed as well as mRNA expression of NRF2 (NFE2L2) and ERα (ESR1) in four ovarian cancer and one benign cell line." (PMID 30597961, 2018). "ESR1 signalling in ovarian cancer involves many interconnected pathways including IL6/STAT3, PI3K/AKT, and MAPK1, making it difficult to elucidate the mechanisms directly responsible for E2-stimulated tumour growth." (PMID 29973689, 2018). "Here, ESR1 expression was reduced in different ovarian cancer cells vs. benign cells in vitro (all p < 0.001)." (PMID 30597961, 2018). "Compared with the benign cell line HOSEpiC, ESR1 expression was reduced in all ovary cancer cell lines (all p < 0.001)." (PMID 30597961, 2018). "MASE (mouse ovarian cancer) cells were pre-incubated with an ESR1 specific antagonist, MPP, for 1 h before treatment with E2 for 48 h." (PMID 29196616, 2017). "ESR1 has been found hypermethylated in malignant ovarian tumors and low malignant potential ovarian tumors, but was the least frequent in our training set." (PMID 24086249, 2013). "Reports showed that ISO directly binds to estrogen receptor 1 (ESR1) to suppress ovarian cancer." (PMID 38203840, 2024). "Besides, low PAPSS1 and high ESR1 were associated with improved PFS and OS in platin-based chemotherapy ovarian cancer patients." (PMID 37684671, 2023). "Additionally, in ovarian carcinoma, reduced EZH2 phosphorylation caused by CDK2 inhibition was found to activate downstream ESR1." (PMID 35846880, 2022). "ESR1 is known to involve in various cancers, such as endometrial and ovarian cancers." (PMID 36531045, 2022). "Moreover, the ESR1 gene is frequently methylated in many types of gynecological malignancies such as highly expressed in epithelial ovarian cancer." (PMID 33907495, 2021). "The role of ESR1 in OC remains unclear; some investigators have found hypermethylation in malignant ovarian tumors and low malignant potential ovarian tumors." (PMID 24086249, 2013). "In our previous study, we examined the estrogenic activity of BPA in estrogen receptor 1 (ESR1)-positive BG1Luc4E2 human ovarian cancer cells and found that BPA increased the ESR1-induced luciferase activity in a dose-dependent manner with a lowest observed effect at 100 nM." (PMID 22574217, 2012). "First-degree family histories of breast cancer (OR = 2.65, 95% CI = 1.15 to 6.09) or of breast and/or ovarian cancer (OR = 3.15, 95% CI = 1.44 to 6.91) were both significantly associated with ESR1 A908G mutation positivity (not shown)." (PMID 17553133, 2007). "Besides this study and the case reports mentioned before, there has been a lack of subsequent reports regarding the identification of ESR1 mutations in ovarian cancer." (PMID 38791941, 2024). "Since then, there have been no reports on the detection of ESR1 mutations in ovarian cancer." (PMID 35954453, 2022). "Analysis of ESR1 gene haplotypes in relation to the rs2234693 and rs9340799 polymorphisms showed that the occurrence of TCAG and CCGG systems may be associated with a significant increase in the risk of ovarian cancer (OR 1.98, p = 0.043 and OR 2.45, p = 0.041, respectively)." (PMID 41977420, 2026). "Genes related to estrogen pathways, including ESR1 and ESR2, their coregulator PELP1, and the SRC, play a role in the induction and progression of ovarian cancer." (PMID 40362695, 2025). "Our study showed an inverse correlation of the gene expression between ESR1 and PAPSS1 in Kaplan–Meier plotter platform of ovarian cancer and platin-based chemotherapy ovarian cancer patients." (PMID 37684671, 2023).